DOT1L (DOT1 like histone lysine methyltransferase)
Diseases named in the same sentence as DOT1L in open-access papers (continued):
Sharing a sentence is not in itself a finding about the gene and the disease.
tumor (continued). "The maintenance of a KMT2A fusion-induced transformed state showed high dependence of DOT1L-mediated H3K79 methylation and small-molecule DOT1L inhibitors showed promising anti-tumor activity in vitro and in vivo in preclinical models." (PMID 31681706, 2019). "Here we demonstrate that inhibition of the H3K79 methyltransferase DOT1L selectively kills tumor cells that exhibit this chromosomal rearrangement." (PMID 30548174, 2019). "DOT1L inhibition has been suggested as an antitumor strategy for the development of active immunotherapies using tumor antigen‐loaded DCs, but exploration of this avenue has become stagnant." (PMID 30628173, 2019). "In summary, our data provide the evidences that epigenetic downregulation of c-Myc by DOT1L silencing or inhibition induces significant cell proliferation suppression, cell cycle arrest at S phase, and inhibits tumor growth in vivo." (PMID 31888761, 2019). "The results showed that the tumor volumes and weights of all DOT1L silenced tumors in the nude mice were significantly smaller or lighter than the control groups, respectively." (PMID 31888761, 2019). "In DLBCL samples, the percentage of DNMT3A-positive tumor cells varied between 0% and 100% and the percentage of DOT1L-positive tumor cells between 1% and 85%." (PMID 29721185, 2018). "Secondly, Dot1l has regulatory functions in gene transcription, which has a tight relationship with tumor genesis." (PMID 27713173, 2016). "Our study focused on the connections between Dot1l expressions and the clinical outcomes of ccRCC patients, and confirmed the regulatory functions of Dot1l on tumor progression indirectly." (PMID 27713173, 2016). "Collectively, we suggest that DOT1L andc-Myc-p300 complex cooperation is critical for tumour initiation and progressionlinking the EMT and CSC phenomenon as a crucial mechanism of EMT-TF induction." (PMID 26199140, 2015). "DOT1L also accelerated in vitro and invivo tumour growth as assessed by soft-agar colony-forming assay andxenograft." (PMID 26199140, 2015). "We next assessed whether the STING pathway is involved in the anti-tumor effect of DOT1L inhibition." (PMID 41299712, 2025). "This suggests that adding DOT1L inhibition may enhance the beneficial effects of chemotherapy and tumor immunotherapy." (PMID 41299712, 2025). "Next, the subcutaneous transplantation tumor model was constructed to further confirm whether the knockdown of DOT1L could counteract BHB treatment in vivo experiments." (PMID 38910244, 2024). "Next, we assessed whether aberrant DOT1L expression interfered with the tumor response to Olaparib treatment in a xenograft mouse model." (PMID 38778348, 2024). "Our results suggest that DOT1L may serve as a novel biomarker for tumor development and a potential target for PARPi diagnosis and drug resistance in OC." (PMID 38778348, 2024). "Context-dependent functions in tumor biology have also been described for DOT1L." (PMID 36425063, 2022). "In addition, the DOT1L activity enhances the neoplastic transformation of CSCs, closely associated with EMT, drug resistance, and high tumor relapse." (PMID 35495127, 2022). "Moreover, analysis of RNA-seq data from ICGC expression profiling dataset revealed positive correlation of MEN1 and DOT1L mRNA expression in OC tumours indicating to existence of a subset of OC tumours that expresses both proteins." (PMID 36333801, 2022). "The DOT1L expression showed a moderate correlation with H3K79 methylation in the tumor sections." (PMID 34887387, 2021). "In addition to EZH2 and SETD2, KMTs such as G9a, MLL, DOT1L and NSD1 are associated with tumor development and progression." (PMID 32859239, 2020). "Furthermore, using ChIP-qPCR on PDX tumor tissue, we detected AR, DOT1L and H3K79me2 at this MYC enhancer in addition to the active enhancer marks H3K27ac and H3K4me2 and RNA polymerase II (Pol II)." (PMID 32814769, 2020).
tumor (continued). "Having dissected the relevance of DOT1L(K358) acetylation on tumorigenesis and metastasis in cells and mice, we wanted to know whether there exists any correlation between DOT1L(K358) acetylation levels and tumor incidence or metastasis in humans." (PMID 32042335, 2020). "Silencing of DOT1L with DOT1LsiRNA and/or miR-10b with antagomirs (an anti-miR-10 inhibitor) significantly decreases the amount of miR-10b production resulting in downregulation of RhoC expression and tumor cell migration/invasion." (PMID 31293964, 2019). "Taken together, these results demonstrated that DOT1L inhibitors could inhibit tumor growth in vivo." (PMID 28114995, 2017). "In order to find out whether the Dot1l expression is connected with tumor characters, we evaluated the Dot1l expression by immunohistochemical staining analysis in all 282 patients’ samples first." (PMID 27713173, 2016). "Dot1l was predominantly expressed in the nucleus of tumor cells." (PMID 27713173, 2016). "With those probable mechanisms, some Dot1l inhibitors were studied for anti-tumor treatment." (PMID 27713173, 2016). "We speculate that expression of DOT1L affects tumor prognosis." (PMID 38495505, 2024). "Simultaneous inhibition of menin, DOT1L, and BAZ1B synergistically slows the proliferation of both antiestrogen-sensitive and -resistant ER-positive cell lines, further supporting menin’s function as a tumor promoter through its association with epigenetic modifiers." (PMID 39336822, 2024). "Additionally, targeting newer GSC-specific markers, such as the stem-like cell marker SOX2 that promotes tumour progression or SOCS3, USP8, and DOT1L, which were recently linked to GSC growth, may be more efficient." (PMID 38136335, 2023). "In addition to the ETV6-NTRK3 gene fusion, PGR, TERT, DOT1L, KDM5A and LRP1B mutations may be passenger mutations that promote tumor progression." (PMID 36585729, 2022). "To determine whether C/EBPβ-mediated cisplatin resistance was dependent on the effect of C/EBPβ in regulating H3K79 methylation, we inhibited DOT1L expression by transfecting DOT1L shRNAs into tumor cells or blocked DOT1L activity using the small-molecule inhibitors SGC0946 and EPZ00477734." (PMID 29712898, 2018). "Furthermore, DOT1L regulates the transcription of G1 phase genes CDK6 and CCND3 through H3K79 dimethylation; therefore, blocking DOT1L could result in G1 arrest and thereby impede the cell proliferation in vitro and tumor growth in vivo." (PMID 28114995, 2017). "Most importantly, we found that downregulation of HA-activated DOT1L signaling or miR-10b production by treating CSCs with DOT1L siRNA or anti-miR-10b inhibitor, respectively, not only reduces RhoGTPase (RhoC) expression and impairs tumor cell migration/invasion but also enhances chemosensitivity." (PMID 28837080, 2017). "However, clinical evidence for role of DOT1L in breast cancerprogression is still unclear." (PMID 26199140, 2015). "The compromised immune set point of DOT1L-null NK cells was evident in their inability to expand in response to MCMV infection and their impaired cytotoxicity against various tumor cells." (PMID 40410571, 2025). "DOT1L and LSD1 co-bound regions included several critical transcription factors and tumor suppressors and knockout of DOT1L in turn led to reduction of LSD1 binding at these sites." (PMID 40781484, 2025). "In any case, further studies of KMT2A/MLL1, DOT1L and STAT3 dependency across a range of ETS-driven mouse and human tumor models are warranted, particularly with the potential for near-term translational impact using existing clinical-grade inhibitors." (PMID 40858905, 2025).
tumor (continued). "DOT1L also correlated significantly with TMB (P=8.45E-06), MSI (P=0.001), and tumor proliferation index (P=7.17E-09) in the TCGA and GTEx datasets." (PMID 38495505, 2024). "The authors further demonstrated that DOT1L is needed for MNA NB cell proliferation, and its suppression reduced NB tumor progression in xenograft tumor models." (PMID 38069407, 2023). "Among 31 single HMTs with expression in all samples, 19 showed a marked up-regulation in RB1-mutant tumours, with particularly notable up-regulation of EZH2, DOT1L, and NSD2, while only 5 displayed a clear down-regulation." (PMID 37883365, 2023). "Overexpression of DOT1L (the H3K79 methyltransferase), upregulated Rho GTPases and survival proteins in CSCs of HNSCC enhance tumor invasion and chemotherapy resistance." (PMID 34051847, 2021). "By recruiting the methyltransferase DOT1L, C/EBPβ can maintain an open chromatin state by H3K79 methylation of multiple drug-resistance genes, thereby augmenting the chemoresistance of tumor cells." (PMID 29712898, 2018). "Immunofluorescence confirmed stable expression of melanocytic marker Melan-A across all groups, indicating that PIEZO1 or DOT1L knockdown did not alter the lineage identity of the tumor cells." (PMID 41533929, 2025). "If this was the case, DOT1L could present as an alternative epigenetic target for destabilising Treg cells in the TME, where they act as a barrier to effective anti-tumour immunity." (PMID 38962004, 2024). "Neither DOT1L expression nor levels of methyltransferases responsible for K9 dimethylation showed statistically significant changes in all tumor types." (PMID 37569534, 2023). "In our third patient, the primary tumor showed a combination of TSC1, CUL3, DOT1L and SETD2 gene mutations (but not BAP1), whereas the PM had the same genetic mutations plus BAP1 mutation." (PMID 34885018, 2021). "In the patient without VHL mutation, we found alterations in CUL3, DOT1L, SETD2 and TSC1 in the primary tumor, with the addition of BAP1 gene mutation in its analyzable PMs." (PMID 34885018, 2021). "In tumor tissue lysates, there was no clear correlation between the DOT1L expression and H3K79 methylation, suggesting that aberrant expression of DOT1L in RB tumors does not exert much effect on global H3K79 methylation." (PMID 34887387, 2021). "Overall, we consider that CBP/DOT1L could serve as a prognostic biomarker for CRC and help guide tumor combination therapy targeting epigenetic modulators." (PMID 32042335, 2020). "Additionally, biochemical analyses of primary tumor tissues identified protein expression correlations between the antitumor activity of 9l and its EMT regulatory effects via DOT1L-catalyzed H3K79 methylation." (PMID 33379275, 2020). "One possible reason is that some remaining DOT1L activity and H3K79 methylation might be required to induce apoptosis in the tumor cells." (PMID 31304633, 2019). "As recently more and more research groups devote to explore molecule targeting inhibitors of histone methyltransferase, such as EZH2- H3K27 inhibitor EPZ – 6438 and DOT1L- H3K79 methylation inhibitors EPZ– 5676, it has become a promising target for anti-tumor therapy." (PMID 27144429, 2016). "Most striking were the large distances seen between PAD14, HDAC10 or DOT1L to other genes in the benign tissue dataset, with only PADI4 remaining isolated in the tumor tissue, suggestive of new tumorigenic transcriptional networks involving HDAC10 and independently, DOT1L." (PMID 27863398, 2016). "In the other hand, Dot1l failed to predict tumor outcomes in pT (3+4) group (P<0.001), Fuhrman grade (3+4) group (P=0.079, P=0.113) and SSIGN/Leibovich (≥4) group (P<0.001)." (PMID 27713173, 2016). "In addition, DOT1L inhibition can down-regulate expression of EMT genes and reduce in vitro cell migration and Matrigel invasion, showing the potential to inhibit tumor metastasis." (PMID 25359765, 2014).
tumor (continued). "DOT1L inhibitors 1 and 2 can inhibit cell migration as well as Matrigel invasion of MDA-MB231 by ~50% and 25%, respectively, indicating the potential of these compounds to inhibit tumor metastasis." (PMID 25359765, 2014). "Moreover, the combination of SGC0946 and GSK343 significantly reduced tumour growth in comparison to single agent therapy, suggesting combined inhibition of EZH2 and DOT1L may represent an effective therapeutic approach for NB patients." (PMID 39501501, 2024). "Here we show that combined inhibition of EZH2 and DOT1L HMTs with the small molecule inhibitors, SGC0946 and GSK343, synergistically drive a rapid ER stress response in NB cells, amino acid depletion, and reduced tumour growth in preclinical models suggesting a novel therapeutic strategy for NB." (PMID 39501501, 2024). "In addition to the 8 representative PKMTs with tumor suppressor activity, PRDM16, MLL2, MLL4, SET domain bifurcated histone lysine methyltransferase 1 (SETDB1), SETD3, NSD1, NSD3, DOT1L, SUV39H1, and SUV39H2 have also been suggested to possess tumor suppressor activity." (PMID 38036730, 2023). "A possible explanation is that the simultaneous deletion of Dot1L and Hdac1 results in the generation of a different class of tumor that does not depend on H3K79 methylation but has acquired other, possibly epigenetic, events that allow oncogenic transformation." (PMID 31304633, 2019). "The full genetic deletion of Dot1L did not reduce tumor burden." (PMID 31304633, 2019). "By recruiting the methyltransferase DOT1L, CCAAT/enhancer-binding protein β (C/EBPβ, also known as CEBPB) could maintain an open chromatin state (H3K79 methylation) at multiple drug-resistance genes, thereby augmenting chemoresistance of tumor cells." (PMID 29712898, 2018). "Moreover, observing H3K79me in transplanted tumor tissues of mice was challenging based on DOT1L knockdown whether injection of BHB or not, which confirmed that DOT1L knockdown successfully caused the blockage of H3K79me." (PMID 38910244, 2024). "Furthermore, DOT1L regulates the transcription of G1 phase genes CDK6 and CCND3 through H3K79 dimethylation, thereby knocking down of DOT1L could result in G1 arrest and therefore impede the cell proliferation and tumor progression both in vitro and in vivo." (PMID 28114995, 2017). "Furthermore, patients with better differentiation (Fuhrman grade 1+2) could be stratified by Dot1l expression, while those with higher Fuhrman grade (3+4) could not, which suggested that Dot1l could be involved in the tumor differentiation." (PMID 27713173, 2016). "A recent study showed that DOT1L inhibition does not suppress proliferation of TNBC cells in vitro, but it decreases in vivo tumor growth by inhibiting CSC properties." (PMID 41299712, 2025). "The tumor size reduction in the cotreatment group did not involve HMGA2 downregulation in the tumors, as epigenetic repression of DOT1L target genes would require continuous exposure to EPZ5676 as previously demonstrated." (PMID 34887387, 2021). "Consistent with a previous report, the pre-developed DOT1L inhibitor, EPZ-5676, did not affect tumor growth in mice." (PMID 33379275, 2020). "Takentogether, these results suggested that DOT1L is able to induce malignanttransformation of breast epithelial cells, regardless of cooperation with HRAS,as a regulator of tumour-initiating ability of breast CSC." (PMID 26199140, 2015). "Notably, no H3K79 demethylase has been identified up to now and the DOT1L (H3K79 methyltransferase) expression was similar in healthy and tumor cells, thus confirming the inverse relationship between H3K79 trimethylation state and nucleosome turnover rate due to fast cell division." (PMID 37569534, 2023).
infection (9 papers, 2014 to 2024). The state of being infected such as from the introduction of a foreign agent such as serum, vaccine, antigenic substance or organism. "Another group recently used a T-cell-specific Dot1L-deficient infection mouse model and observed that the repressive effect of IFN-γ production by Dot1L was T-bet dependent." (PMID 34305954, 2021). "Infection with human cytomegalovirus, a virus bearing a large double-stranded DNA genome that becomes associated with host cell histones, increases Dot1L expression and H3K79me2, which overlaps with the beginning of viral replication." (PMID 32188146, 2020). "Those Dot1l-deficient B-cells that did make it to maturity were still capable of generating low titres of antibodies, assembling and organising themselves correctly within the secondary lymphoid organs and generating antigen-specific immune responses to immunisation and infection." (PMID 38962004, 2024). "In a murine model of (P. acnes)-primed LPS224-induced fulminant hepatitis, in vivo inhibition of DOT1L using EPZ-5676 protected the mice from succumbing to infection." (PMID 38962004, 2024). "Being a regulator of host innate immune defense, DOT1L function on nucleosomal H3 upon pathogen infection would enable immediate activation of pro-inflammatory pathways for bacterial clearance." (PMID 38129415, 2023). "The enhanced H3K79 mark in DOT1L inhibitor-treated cells upon infection further confirms that the K79 mark at the loci is due to Rv2067c." (PMID 38129415, 2023). "Restoration of NS1 expression in trans also reinstated Dot1L as a regulator of the RIG-I-dependent signaling in delNS1 infections." (PMID 32188146, 2020). "Consistent with the results for the DOT1L protein, the relative mRNA levels of DOT1L also showed a significant increase at 36 and 48 hpi compared to those in cells with mock infection." (PMID 33363525, 2020). "The ability of Dot1L to regulate IFN signaling, supports an important and general role of Dot1L in the control of pathogen infections." (PMID 32188146, 2020). "Consistently, the phosphorylation of TBK1, which is involved in the MDA5-mediated IFNβ induction, was increased in DOT1L-KO HD11 cells compared to that in WT cells at 24 h post-infection with ALV-J." (PMID 33363525, 2020). "Cells with up-regulated DOT1L expression were infected with influenza virus at 10−3 pfu/cell (PR8 Dot1L) and viral titters were analyzed by plaque assay at different times post-infection." (PMID 31727944, 2019). "Thus, as a regulator of the innate immune response, DOT1L seems to be an integral component of the host defense arsenal against a variety of infections." (PMID 38129415, 2023). "In this study, we found that p38 MAPK was activated by HSV-1induced infection, and inhibition of Dot1l could suppress p38 MAPK activation in HCE cells." (PMID 33628364, 2021). "We firstly analyzed the expression of DOT1L in HD11 cells in response to the infection with ALV-J." (PMID 33363525, 2020). "From this study we concluded that methylation of H3K79 by DOT1L has an important role in the control of the interferon signaling and may modulate the infection of different pathogens." (PMID 31727944, 2019). "Following infection, changes in expression of Actn4, Aldha1 and Dot1L were examined by qPCR." (PMID 24983472, 2014). "The host-factors relevant for infection, such as TRIM25, seem to be a target for Dot1L modulation even in uninfected cells." (PMID 32188146, 2020). "In agreement with our previous report, EPZ treatment did not significantly interfere with ISG induction at this early time post-infection, as 16 h are required to restrict ISG induction by Dot1L inhibition." (PMID 32188146, 2020). "Infection of human primary fibroblasts with human cytomegalovirus (HCMV), produces a marked increase in H3K79me2 levels and downregulation of Dot1L expression results in a decreased viral growth." (PMID 29352168, 2018).